AR (androgen receptor)
Diseases named in the same sentence as AR in open-access papers (continued):
Sharing a sentence is not in itself a finding about the gene and the disease.
prostate carcinoma (continued). "In situ Hi-C maps confirm that the enhancer–promoter interactions are more frequently detected in 22Rv1 prostate cancer cells than in RWPE1 normal cells; there are also cancer-specific smaller-size TADs near the AR gene." (PMID 31515496, 2019). "Of note, the amount of AR expressed in MDA-MB453 was higher than that observed in MDA-MB231 cells and similar to that detected in prostate cancer-derived LNCaP cells." (PMID 30872694, 2019). "Moreover, PARP may promote the transcriptional activity of AR in prostate cancer." (PMID 31357527, 2019). "In fact, it has been shown that downregulation of Tip60 or Tip60-defective mutant decreases AR activation and reduces PSA mRNA levels induced by androgen in LNCaP cells or in androgen-insensitive prostate cancer cells." (PMID 31671779, 2019). "To illustrate the sensitivity of the optimized protocol, we provide high-quality ChIP-seq data for three independent factors (AR, FOXA1, and H3K27ac) from a single core needle prostate cancer biopsy specimen." (PMID 30620009, 2019). "On the contrary, NDRs in prostate cancer-specific enhancers involved in enhancer–promoter loops are enriched for motifs for TFs such as FOXA1, GRHL2, ETS, and AR." (PMID 31515496, 2019). "Microarray analysis of prostate (cancer) specimens showed that, similarly to AR expression, UBE2C and BUB1B are significantly upregulated in CRPC tissue compared with benign tissues and androgen-sensitive primary prostate cancer and metastatic tissues." (PMID 30664691, 2019). "Subsequent studies have shown that CaMKKβ is a key effector of the androgen receptor in stimulating glycolysis through the activation of AMPK and phosphofructokinase (PFK), which drives anabolism and proliferation of prostate cancer cells." (PMID 30621060, 2019). "Responses to PARPi have been detected in combination with androgen receptor inhibitors in prostate cancer also in patients without obvious mutations causing HR defect in tumors, suggesting that blocking AR signaling may induce clinically relevant state of BRCAness to tumors." (PMID 31357527, 2019). "Further, the treatment of SeNP reduces the expression of androgen receptor (AR) and prostate-specific antigen (PSA), the key players of the initiation and progression of prostate cancer." (PMID 32010628, 2019). "In prostate cancer, β-arr2 inhibits cell viability and proliferation by downregulation of FOXO1 and represses AR signaling, and AR expression/activity negatively correlates with β-arr2 expression." (PMID 30837880, 2019). "Our data show that AR-expressing prostate cancer cells (LNCaP, 22Rv1, and VCaP) are more sensitive to CWP232291 than AR-negative prostate cancer cells (PC3 and DU145)." (PMID 31387608, 2019). "TSPX overexpression represses the expression of AR target genes, including KLK2 and KLK3, in a prostate cancer cell line LNCaP." (PMID 30863497, 2019). "We have previously reported that deubiquitinase USP14 stabilizes AR proteins by deubiquitination and USP14 inhibition results in inhibition of cell growth and tumor progression in AR-positive prostate cancer and breast cancer." (PMID 31126320, 2019). "Androgen receptor (AR) signaling has been shown to bring the androgen regulated gene TMPRSS2 and the ERG gene in close proximity in prostate cancer cell line models." (PMID 31106278, 2019). "Interestingly, other studies indicated ASC-J9® could also suppress prostate cancer progression via an AR-independent mechanism involving the suppression of STAT3-CCL2 signaling, which could explain why ASC-J9® could also suppress both BCa AR-positive TCC-SUP cells and AR-negative J82 cells." (PMID 31234917, 2019). "Our current results also demonstrated that AL can reduce the expressions of 5AR and AR in both TP-induced BPH rats and LNCaP prostate cancer cells, suggesting the inhibitory effect of AL on the androgen pathway during the pathogenesis of BPH." (PMID 31467577, 2019).
prostate carcinoma (continued). "The antagonistic relationship at the gene expression level was observed between AR and MYC in prostate cancer context." (PMID 31581661, 2019). "Bacillus licheniformis derived biogenic SeNPs are very effective in inducing prostate cancer cell death at a minimum concentration of 2 μg Se/ml through a TNF/IRF1 mediated necroptosis pathway and by AR down-regulation." (PMID 32010628, 2019). "In prostate cancer (PCa) cells, LSD1 mediates the transcriptional activity of androgen receptor (AR), a ligand dependent nuclear transcription factor that drives PCa initiation and progression to the castration-resistant prostate cancer (CRPC)." (PMID 31428587, 2019). "In 2018, a phase 2 trial (NCT01972217) confirmed the efficacy of double blockade of AR and PARP in metastatic, castration resistant prostate cancer patients." (PMID 31737426, 2019). "Below an overview on the role of AR in different cells composing TME and its involvement in prostate cancer disease is reported." (PMID 31616657, 2019). "Our previous study also found that MAGE-A11 and AR cooperated in the upregulation of FSTL1 to promote growth and progression of castration-resistant/recurrent prostate cancer." (PMID 31598157, 2019). "The results presented herein demonstrate that the NGGAs, VNPP414 and VNPP433-3β, are promising anti-prostate cancer molecules and are more effective than their parent molecule, Gal and the FDA-approved anti-AR drug, enzalutamide." (PMID 31653008, 2019). "The molecule had an antiproliferative effect which was greater in AR-positive (low nanomolar range, IC50 0.010 ± 0.001 μM) than in AR-negative prostate cancer cell lines." (PMID 30682828, 2019). "Although fusion of the AR regulated TMPRSS2 promoter to ETS related gene (ERG) that results in ERG overexpression is a common event in CA prostate cancer patients (50–70%), it is less frequent among AA and other ethnic groups." (PMID 31741711, 2019). "Interestingly, a recent study showed that metastatic prostate cancers are heterogeneous for that concerns AR/AR signaling expression and neuroendocrine features and, according to these two parameters, can be subdivided into three subgroups: AR+/NE-, AR-/NE+, and AR-/NE-." (PMID 31366128, 2019). "Similar reciprocal feedback has been reported between androgen receptor signaling and PI3K in prostate cancer, suggesting a common theme between hormone receptor signaling and PI3K in BC and prostate cancer." (PMID 31336602, 2019). "Critically, IRC117539’s off-target activity as a proteasome modulator was observed in both AR-positive (LNCaP and VCaP) and AR-negative (PC3 and Du145) prostate cancer cells alike." (PMID 31431473, 2019). "In support of our findings, recent studies have reported that Menin, a critical co‐activator of androgen receptor (AR), along with MLL complex is recruited to the promoter of AR by BAP18 to promote its transcriptional activation and drive prostate cancers." (PMID 30548174, 2019). "ANCCA, a co-activator of androgen receptor (AR), can bind E2F and enhance E2F-mediated EZH2 transcription in prostate cancer cells." (PMID 29556394, 2018). "Therefore, in response to androgen/AR-targeted therapy in hypoxia, prostate cancer cells most capable of redirecting glucose flux from PPP to glycolysis may maintain glucose metabolism and utilization, thereby gaining survival and growth advantage and evading therapy." (PMID 30478344, 2018). "BET proteins enhance the oncogenic functions of major cancer drivers by elevating the expression of these drivers, such as c-Myc in multiple myeloma, androgen receptor (AR) and ETS-related gene (ERG) in prostate cancer, and TWIST in breast cancer." (PMID 30150556, 2018). "Similar results were recently obtained in prostate cancer, in which it has been demonstrated that FOXA1 expression is closely related to prognosis independently of AR level." (PMID 29970021, 2018).
prostate carcinoma (continued). "In prostate cancer cells, androgen receptor and IGF1R form a feedback loop in which AR activates IGF1R, which, in turn, stimulates AR activity." (PMID 29462882, 2018). "Here, we explored the effect of androgen receptor blockade (ARB) on PSMA expression visualized by PET and its potential additive effect when combined with 177Lu-PSMA RLT in a mouse model of prostate cancer." (PMID 30374743, 2018). "Various mechanisms of docetaxel-resistant exist in prostate cancer, such as ABC transporters, glucocorticoid receptor (GR), androgen receptor (AR) splicing, epithelial plasticity and stem cells." (PMID 29460131, 2018). "The results of these assays showed that AR and MYLIP physically interacted in prostate cancer cells." (PMID 29707137, 2018). "Among them, CDK5 was detected to undergo isoform switching between prostate cancer and benign tissues, which suggests an important regulatory role of CDK5 alternative splicing on AR phosphorylation in prostate cancer." (PMID 30367578, 2018). "Here we perform a head-to-head comparison between a currently approved androgen receptor antagonist enzalutamide, and its PROTAC derivative, ARCC-4, across different cellular models of prostate cancer drug resistance." (PMID 30271980, 2018). "Treatment of prostate cancer cells with HDAC3‐specific inhibitor not only inhibits AKT‐mTORC1 signaling, but also suppresses expression of AR and its downstream target genes." (PMID 29523594, 2018). "After virtual screening and the cell proliferation assay validation, the inhibition rate of prostate cancer cell LNCaP and DHT-induced transcriptional activation of AR were detected on a series of pyrazolopyrimidine analogs in vitro." (PMID 30210333, 2018). "In human prostate cancer organoids and xenograft models, we further showed that a selective HDAC3 inhibitor is efficacious in inhibition of AKT and AR signaling in both PTEN‐ and SPOP‐mutant background." (PMID 29523594, 2018). "Treating prostate cancer cells with synthetic androgen R1881 resulted in an increased AR occupancy at the PEG10 promoter, while decreased when treated with AR antagonist Enzalutamide." (PMID 30123090, 2018). "Collectively, these results suggest that HSP70 is significantly overexpressed in advanced stage prostate cancer and the level of HSP70 expression is correlated with AR-V7 and AR-FL expressions." (PMID 30446660, 2018). "C21 reduced the proliferation activity of prostate cancer cells and down-regulated the PSA promoter activity and the AR protein expression." (PMID 29568400, 2018). "A separate study showed that silencing CD44v9 using short hairpin RNA inhibited assembly of p-Met, AR, HSP90, P110α/PI3K, and CD44 into lipid raft-like structures and reversed the assembly of these components in the complex in prostate cancer." (PMID 29747682, 2018). "We recognized that the alpha particle induced DNA damage and relied on ensuing upregulation of AR and KLK2 to addict the prostate cancer to the therapeutic [225Ac]hu11B6 agent." (PMID 29691406, 2018). "Further, the increased expression of AR, KLK3 and AMACR in Patient 1 and 2 suggests the presence of prostate cancer cells within the mixed biopsy population." (PMID 30279484, 2018). "AR‐ and PTEN‐proficient prostate cancer cell lines (CWR22Res, CWR22RV1 and VCaP) showed significantly enhanced expression of AR variants including ARV7 (Figs EV1K and EV2B)." (PMID 29540470, 2018). "Androgen receptor (AR) gene and UPR-related genes expressions, including HSPA5 expression, are correlated in prostate cancer cell, suggesting interplay between the UPR and androgens." (PMID 29932125, 2018). "Since ARBs suppressed AR expression in TRAP rats and the human prostate cancer cell line LNCaP in our previous study, we next investigated the effect of C21 on AR expression in TRAP rats." (PMID 29568400, 2018).
prostate carcinoma (continued). "The Whitte laboratory demonstrated a synergistic interaction between Ras pathway activation and AR signaling that leads to elevated EZH2 expression and expand prostate cancer progenitor cells in vivo." (PMID 29888169, 2018). "In prostate cancer, HER2 signaling has been shown to stabilize AR protein and optimize binding of AR to promoters of androgen-regulated genes, and HER2 pathway inhibition reduces AR transcriptional activity." (PMID 29382369, 2018). "Mutations in SPOP lead to genomics instability and are identified as driver events resulting in tumorigenesis of prostate carcinoma via coordination with PI3K/mTOR and AR (Androgen Receptor) pathway in mouse." (PMID 29986747, 2018). "In particular, CITED2 is suspected to be extensively involved in prostate cancer, since its expression is induced by an ETS family member ELK119, which has been reported to recruit AR to activate growth signaling in prostate cancer cells." (PMID 30291252, 2018). "Our work characterized the expression and splicing profiles of kinase genes in prostate cancer and proposed a hypothetical model on isoform switching of CDK5 and AR phosphorylation in prostate cancer." (PMID 30367578, 2018). "To determine the relationship between HSP70 and AR expression in human prostate cancer, we first analyzed HSP70 and AR-FL expression in GEO and Oncomine databases." (PMID 30446660, 2018). "BMI1 binds the androgen receptor (AR) and prevents MDM2-mediated AR protein degradation, resulting in sustained AR signaling in prostate cancer cells." (PMID 29402932, 2018). "ACK1 has been shown to be critical for progression of PC to hormone therapy insensitive stage called castration resistant prostate cancer or CRPC due to it’s ability to regulate the expression and function of AR in androgen-independent manner." (PMID 29386546, 2018). "In this study, we investigated the clinical importance and link between AR, EGFR and MMP-9 in prostate cancer by using clinical tissues from prostate cancer patients and prostate cancer cell lines." (PMID 30134822, 2018). "Moreover, knockdown of the expression of AR in LNCaP and 22Rv1 cells resulted in abrogation of melatonin receptor-mediated cell proliferation inhibition, indicating that the antiproliferative signaling pathway activated by melatonin in human prostate cancer cells is AR-dependent." (PMID 29783631, 2018). "In prostate cancer, GSK3 has been shown to inhibit androgen receptor-stimulated cell growth, whereas high expression levels of GSK3 have been shown to participate in NF-κB mediated cell survival in pancreatic cancer." (PMID 29963225, 2018). "Specifically, AR-mediated activation of SPDEF repressed expression of TGFBI and CCL2, key drivers of prostate cancer metastasis." (PMID 30200227, 2018). "It was found that both DHT and synthetic testosterone (R1881) stimulation of LNCaP prostate cancer cells and MCF7 breast cancer cells results in AR interaction with C-Src." (PMID 30416486, 2018). "We therefore tested another prostate cancer cell line (22Rv1) and a breast cancer cell line (T47D) and found that ARCC-4 efficaciously degrades AR in all of these cell lines." (PMID 30271980, 2018). "Prostate cancer relays on distinct proliferative pathways, including the PI3K and RAS/RAF pathways downstream of membrane AR activation; dysregulation of these pathways in both early and late stage prostate cancer was demonstrated through genomic profiling." (PMID 30719023, 2018). "Castration is the first line of therapy for prostate cancer patients in the clinic and SOX9 has been proposed to interact with AR." (PMID 29484136, 2018). "The results are expected to reveal the interaction mechanism of DC3-AR complex, promote the development of DC3 and correlative cyclopeptide AR antagonist, which will contribute to the rational drug design for prostate cancer." (PMID 29755968, 2018).
prostate carcinoma (continued). "For example, SPOP acts as a cancer suppressor in prostate cancer by promoting the proteasomal degradation and ubiquitination of the SRC-3 (p160 steroid receptor coactivator-3) protein, thus suppressing androgen receptor transcription activity." (PMID 30607139, 2018). "Increased surrounding infiltrating bone marrow mesenchymal stem cells directly suppress AR expression through CCL5/HIF2α pathway and CCL5 from the bone microenvironment has been shown to promote the growth of prostate cancer bone metastases." (PMID 30200999, 2018). "Previous studies showed that BBR suppresses both AR signaling pathway and ERK-mediated proliferation in prostate cancer cells." (PMID 30061836, 2018). "In prostate cancer cells EMT is induced by TGF-β and/or androgens, with a threshold AR level determining the phenotypic outcome and invasive properties." (PMID 29562686, 2018). "With ChIP-chip and CAGE (cap analysis of gene expression) analysis, which are advanced high-throughput techniques, several new AR target genes, including TRIM36, have been identified in the whole genome of prostate cancer cells." (PMID 29449534, 2018). "In this study, we made the unexpected observation that AR protein levels, but not transcript levels, as well as the protein and transcript levels of AR-activated targets PSA and TMPRSS2, were decreased by depletion of BMI1 in AR-positive prostate cancer cells." (PMID 29402932, 2018). "AR blockade with enzalutamide, an anti-androgen currently FDA approved in prostate cancer, decreased MCL cell proliferation, prompting the opening of a phase II trial to clinically investigate this effect." (PMID 30109020, 2018). "We recognized that the α-particle induced DNA damage and ensuing upregulation of AR and KLK2 would increase the prostate cancer targeting by [225Ac]hu11B6, creating an amplification loop for cell-specific therapy." (PMID 29691406, 2018). "Our overall results demonstrate a role for CREB3L4 in modulating AR action, suggesting an interrelationship, and an AR-ER stress-CREB3L4 signaling axis, in prostate cancer cell proliferation." (PMID 28338058, 2017). "The ability to cooperate with the AR highlights a potential role of KDM3A as coactivator and driving force for sex-specific tissue development as well as for prostate cancer initiation and progression." (PMID 28416760, 2017). "For example, the CD44+α2β1+CD133+ cells purified from human prostate tumor samples, the CD44+ cells in several prostate cancer xenografts, and the BCRP+ putative PCSCs are all AR-." (PMID 28400729, 2017). "In prostate cancer cell lines, KDM3A promotes androgen receptor activity that in turn upregulates c-Myc expression and also inhibits the E3 ubiquitin ligase HUWE1 which prevents c-Myc protein degradation." (PMID 29156681, 2017). "Using high-throughput drug screening, we found that YM155 synergized with high-dose androgen therapy in prostate cancer cells, and that this interaction was mediated by direct transcriptional upregulation of SLC35F2 by AR." (PMID 28350329, 2017). "The androgen receptor and PI3K pathways are the two most commonly deregulated pathways in prostate cancer." (PMID 28420128, 2017). "In LNCaP prostate cancer cells, EGFR was shown to induce Src interaction with AR through the proline-rich 372–379 region within the SH3 domain." (PMID 28671964, 2017). "In this study we show that ING3 regulates the AR pathway in prostate cancer by virtue of acting as a scaffolding component of the TIP60 complex, promoting AR acetylation, its nuclear translocation, and the activation of androgen-responsive genes." (PMID 28511652, 2017). "Together these results show that both inhibition of AR and androgen deprivation lead to significantly increased CXCR7 transcription in androgen-responsive prostate cancer cells." (PMID 28596572, 2017).